C11orf21 (chromosome 11 open reading frame 21)
Tractability: No criterion of Open Targets' tractability assessment is met for any kind of drug.
Gene: Protein-coding gene on chromosome 11 (2,295,628 to 2,303,180, reverse strand). Ensembl gene ENSG00000110665.
Subcellular location: Cytoplasm
Subcellular location (Human Protein Atlas): Nucleoplasm; Cytosol
Gene Ontology:
Cellular component: cytoplasm
Genetic constraint (gnomAD): Loss-of-function variants: 19 observed, 14.52 expected, observed/expected ratio (o/e) 1.31, 90% interval 0.91 to 1.83. The upper end of that interval is the gene's LOEUF score, 1.83, which puts it in group 6 of 6, group 1 being the genes least tolerant of losing a copy. Missense variants: 171 observed, 176.47 expected, observed/expected ratio (o/e) 0.97, 90% interval 0.86 to 1.1. Synonymous variants: 62 observed, 68.73 expected, observed/expected ratio (o/e) 0.9, 90% interval 0.73 to 1.11.
Homologues: Orthologues: chimpanzee C11H11orf21 (86% identical), macaque C11orf21 (71% identical).
Diseases named in the same sentence as C11orf21 in open-access papers:
C11orf21 is named in the same sentence as 1 disease in open-access papers, as found by Europe PMC text mining. Sharing a sentence is not in itself a finding about the gene and the disease. The quoted sentences say what the papers report.
cancer (2 papers, 2022 to 2025). A tumor composed of atypical neoplastic, often pleomorphic cells that invade other tissues. "TSPAN32 and C11orf21, both located in the 11p15.5 imprinted region on chromosome 11, play key roles in haematopoietic regulation and cancer." (PMID 41421321, 2025). "In the 8-mRNA signature (KCNJ18, RPE65, GRIA1, LCN15, C11orf21, ANXA13, FSIP2 and KRT76), the expressions of some mRNAs have been reported to have significant associations with the survival in some cancers." (PMID 35675043, 2022).